IL6 (interleukin 6)
Diseases named in the same sentence as IL6 in open-access papers (continued):
Sharing a sentence is not in itself a finding about the gene and the disease.
Obesity (continued). "Pro-inflammatory cytokines like TNF-α and IL-6 are linked to obesity." (PMID 38473961, 2024). "In addition, elevated levels of these mediators (such as tumour necrosis factor or interleukin 6) cause placental inflammation, with detrimental effects on fetal metabolism, and increase the risk of metabolic syndrome and obesity in the long term." (PMID 38248859, 2024). "Thus, knock-out mice for IL-6 (IL-6−/−) are less susceptible, compared to the WT strain, to the enhancing effect of obesity on HCC development." (PMID 39456575, 2024). "The blocking of IL-15 and IL-6 in humans and mice is associated with obesity." (PMID 39769263, 2024). "Researchers place IL-6 polymorphisms, such as rs1800795 and rs1800796, as risk factors for obesity." (PMID 38397196, 2024). "Furthermore, the inflammatory pathways activated in PsO, including increased TNF-α, IL-6, and other pro-inflammatory cytokines, are also implicated in the pathogenesis of obesity and metabolic syndrome." (PMID 39697959, 2024). "IL-6 polymorphisms have been linked to obesity in numerous studies." (PMID 38397196, 2024). "In addition, elevated PAI-1 levels have been linked to the impairment of insulin signaling in obesity and in the establishment of a chronic inflammatory state, similar to the role played by IL-6, also upregulated in our model." (PMID 38396763, 2024). "As a metabolic pathogenic status, obesity is often accompanied by systemic chronic low-grade inflammation and elevated levels of immune markers such as leptin, IL-6, and TNF, which may influence tumor growth." (PMID 39165513, 2024). "The causal link between obesity and IR lies in the elevated levels of proinflammatory adipokines, such as IL-6 and TNF-α, released by adipose tissue following fat accumulation, which worsens tissue responses to insulin, thus resulting in T2D, dyslipidemia and hypertension." (PMID 38133765, 2024). "Several cross-sectional studies indicated associations between serum 25(OH)D concentration and inflammatory markers: In Spanish school children, low serum 25(OH)D was associated with high IL-6 in children with overweight/obesity as well as with increased CRP in children with obesity." (PMID 39231874, 2024). "Interestingly, we observed that CRP mediated the association of obesity (i.e., increased BMI and WC) with acute bronchitis and pneumonia, while IL-6 mediated the effects of BMI and WC on pneumonia." (PMID 39337223, 2024). "Moreover, cardiovascular complications and atherosclerotic disease were frequently associated with DM and obesity, and IL-6 and TNF-α levels were elevated in human atheromatous lesions." (PMID 39408723, 2024). "Additionally, both mice with diet-induced obesity and human subjects with obesity demonstrated heightened levels of IL-6, which are predisposing factors in Th17 lineage expansion, consequently leading to an increase in the number of CD4+ cells secreting IL-17." (PMID 39125666, 2024). "explored for the first time this relationship in adulthood, describing increased circulating zonulin levels in patients with glucose intolerance and obesity-associated IR versus controls, and enhancing the role of subclinical inflammatory cytokine IL-6 in this pathway." (PMID 38405153, 2024). "Moreover, HFD feeding is associated with an overexpression of IL-6 in the liver that contributes to the low-grade inflammation process observed in obesity." (PMID 37107352, 2023). "Obesity-associated dysfunctional adipose tissue (AT) also secretes pro-oncogenic factors such as TNFα, IL-6, IL-1β and provides a carcinogenesis-promoting microenvironment for breast cancer development and progression; it is therefore a fundamental factor of postmenopausal breast cancer development." (PMID 36774339, 2023). "Obesity causes mild inflammation and can hasten the development of chronic diseases and their complications by secreting pro-inflammatory cytokines such as interleukin-6 (IL-6), tumor necrosis factor (TNF), and C-reactive protein (CRP)." (PMID 37275644, 2023).
Obesity (continued). "The chronic inflammatory reaction caused by obesity and the increase in interleukin-6 may also increase the risk of other cancers." (PMID 36836694, 2023). "In obese patients, aberrant methylation of the IL-6 gene promoter is greatly enhanced, suggesting that it may be implicated in obesity’s pathophysiology." (PMID 37020540, 2023). "It is well established that adults with obesity may also have elevated levels of systemic inflammation, and that weight loss interventions decrease circulating inflammatory markers such as interleukin-6 (IL-6) and tumor necrosis factor-alpha (TNF-α)." (PMID 38068805, 2023). "Obesity however is associated with chronic low-grade inflammation possibly from hypoxia in adipocytes, resulting in the release of IL-6 and activation of other factors that positively feedback and amplify IL-6 release." (PMID 36200436, 2023). "Healthy lifestyle, including leisure time physical activity, healthy diet, and weight loss can improve energy balance and may reduce obesity-related inflammation, such as IL-6, TNF-α, and CRP." (PMID 37764780, 2023). "Moreover, chronic activation of IL-6/IL-6R signaling in adipose tissue was linked to the development of obesity-related metabolic disorders, such as insulin resistance and type 2 diabetes." (PMID 37781401, 2023). "Notably, IL-6 produced by visceral adipose depots is drained directly into the portal circulation and contributes to obesity-associated production of C reactive protein (CRP), a clinical index of cardiovascular risk." (PMID 37509065, 2023). "Of note, IL-6-deficient mice developed late-onset obesity and systemic glucose intolerance." (PMID 38136564, 2023). "Similarly, obesity is known to cause a chronic inflammatory state, even within the airways, through the release of IL-6 from adipocytes and facilitating the release of other pro-inflammatory cytokines and the generation of reactive oxygen species." (PMID 36699806, 2023). "Regarding the role of specific proinflammatory cytokines and adipokines, a study in a mouse model of chemically induced colitis-associated colorectal cancer (CAC) showed that diet-induced obesity increased IL-6 levels, thereby favoring macrophage polarization towards tumor-promoting M2 macrophages." (PMID 36670988, 2023). "As human obesity is also associated with increased local and systemic IL-6 levels, these data argue that altered cytokine production more broadly may drive niche formation to support metastatic spread in obesity." (PMID 37648285, 2023). "IL-6 knockout prevents BMSCs senescence and alleviates obesity-induced bone loss." (PMID 37891477, 2023). "Taken together, we propose that NEGR1 may play a regulatory role in IL-6 signaling by interacting with IL-6R, which may contribute to a molecular link underlying obesity, inflammation, and the depression cycle." (PMID 37187893, 2023). "Considering that astrocyte-specific IL-6 knockout mice showed increased body weight, and cerebral IL-6 overexpressing mice resisted diet-induced obesity, IL-6 might be a key cytokine associated with astrocyte function by regulating several circRNAs in obesity." (PMID 37047207, 2023). "Obesity induced inflammation is also associated with age-related muscle wasting and sarcopenia, skeletal muscle disuse and catabolism: for instance, chronically elevated IL-6 activates the JAK/STAT3 pathway leading to skeletal muscle atrophy." (PMID 37624550, 2023). "We speculated these effects originated from the antioxidant and anti-inflammatory activity of OSO, which following the published article suggesting an association between obesity and oxidative stress, lipid metabolism, and IL-6." (PMID 37371970, 2023). "First, retinol-binding protein 4 is enriched in obesity-associated exosome-like vesicles, which further stimulates the differentiation of peripheral blood monocytes into activated M1 macrophages with increased secretion of IL-6 and TNF-α." (PMID 36593475, 2023).
Obesity (continued). "A major underlying factor driving the pathogenesis in obesity and metabolic syndrome is the presence of a chronic low-grade inflammation, which is characterized by increased circulating IL-6 and other cytokines, as well as altered levels of adipokines, such as leptin and adiponectin." (PMID 37841878, 2023). "The prevalence of obesity is increasing rapidly worldwide, causing susceptibility to pro-inflammatory state by increasing inflammatory mediators, such as Tumor Necrosis Factor-alpha (TNFα), and Interleukin-6 (IL-6), and reducing the level of adiponectin." (PMID 37246210, 2023). "Elevated concentrations of markers and mediators of inflammation and acute-phase reactants, including C-reactive protein, interleukin (IL)-6, and plasminogen activator inhibitor-1, confirmed the epidemiologic associations between inflammation and obesity and type II diabetes." (PMID 37298118, 2023). "This may be associated with the observation that patients with obesity had a trend to lower IL-6 levels (p = 0.06)." (PMID 37626613, 2023). "We propose two potential mechanisms that may explain this relationship: First, obesity is associated with inflammation, which can stimulate the production of proinflammatory cytokines such as IL-6." (PMID 37481511, 2023). "Visceral adipose tissue is also resistant to insulin and leptin and is the site of altered secretion of molecules and hormones such as adiponectin, leptin, resistin, tumor necrosis factor and interleukin-6, which exacerbate cardiovascular disease associated with obesity." (PMID 37081416, 2023). "Meanwhile, chronic inflammation associated with obesity leads to the overexpression of inflammatory adipokines by activated macrophages, such as Interleukin-6 (IL-6) and Tumor Necrosis Factor-Alpha (TNF-α), which are both correlated with cell proliferation and carcinoma migration." (PMID 38068717, 2023). "This evidence may be explained by preclinical data demonstrating that obesity and overweight are associated with an increase in inflammatory cytokines (e.g., IL-6 and TNF-), which represent key mediators in psoriasis." (PMID 37049545, 2023). "In this context, obesity and type 2 diabetes both have a characteristic of increased adiposity linked to a persistent, low-grade systemic inflammation that encourages the aberrant production of proinflammatory cytokines such as IL-6." (PMID 37144176, 2023). "On the other hand, metabolic diseases, such as MAFLD, T2D, and obesity, cause low-grade inflammation through certain proinflammatory cytokines such as TNFalpha and IL-6, which can act as a steppingstone in a vicious cycle of hyperinflammation and cytokine storm, resulting in target organ damage." (PMID 37629728, 2023). "In adult adipose tissue, IL-6 is highly expressed and favorably linked with obesity." (PMID 37251328, 2023). "Conversely, mice deficient in IL-6 develop obesity in the later stages of life." (PMID 37268247, 2023). "In addition, obesity, especially central obesity, is associated with an increase in inflammatory factors such as interleukin 6 and tumor necrosis α, which negatively impact pulmonary function and increase morbidity and mortality." (PMID 35346135, 2022). "Obesity is associated with chronic inflammation, which is characterized by increased levels of several pro‐inflammatory cytokines, including interleukin 6 (IL‐6), tumor necrosis factor‐α (TNF‐α) and C‐reactive protein (CRP)." (PMID 35293040, 2022). "Obesity was also associated with significantly upregulated expression of IL6 in BOB patients." (PMID 36428692, 2022). "Therefore, the literature suggests a constitutive role of IL-6, promoting anti-inflammatory action via its pleiotropic cell type-specific effect in obesity meta-inflammation and its associated metabolic disorders like T2D." (PMID 35326098, 2022). "However, IL-6 is highly associated with overweightness and obesity, both states that are related to chronic low-grade inflammation." (PMID 36139749, 2022).
Obesity (continued). "A study of young European adults concluded that the highest level of physical activity was associated with a lower fat mass, leptin and interleukin 6, and some of the detrimental influence linked with overweightness and obesity was diminished due to physical activity." (PMID 36501003, 2022). "Il-6 is a cytokine with a broad spectrum of physiological functions, including a role in pathophysiology of obesity and its associated states, although its exact role remains unknown." (PMID 36013467, 2022). "Third, obesity is associated with chronic inflammation due to increased pro-inflammatory cytokines and leptin by adipocytes and immune cells, including elevated C-reactive protein, interleukin 6, and ferritin." (PMID 35945221, 2022). "Furthermore, obesity has been identified as a risk factor for developing hepatocellular carcinoma via increased production of IL-6 and TNF." (PMID 35267581, 2022). "The factors related to obesity that negatively influence bone mass are mainly associated with an increase in the percentage of fat mass since obesity is a proinflammatory state that is associated with the secretion of a series of cytokines (IL-6, TNF-α) and adipokines (adiponectin, leptin...)." (PMID 35458178, 2022). "Obesity-associated inflammation in the adipose tissue and liver induces an increase in macrophage infiltration and the expression of pro-inflammatory cytokines such as tumor necrosis factor-alpha and IL-6." (PMID 36470993, 2022). "In obesity and in type 2 diabetes, FAPs can cause chronic inflammation, fibrosis, intramuscular fat accumulation in skeletal muscle and muscle fiber degeneration by secreting pro-inflammatory cytokines as IL-6." (PMID 36499366, 2022). "Moreover, their research on −174G/C polymorphism of the IL-6 gene and obesity in relation to the therapeutic response to TNF-α blockers showed that the polymorphism can be considered a risk factor in the prognosis of psoriasis treatment." (PMID 35330186, 2022). "In OSA, IL-6 has been associated with hypoxemia and obesity." (PMID 35898322, 2022). "Second, elevated levels of TNF- α and IL-6 that have been linked with obesity and type 2 diabetes might impair insulin sensitivity by inhibiting insulin signaling pathways." (PMID 36213511, 2022). "In this respect, IL-6 is a multifunctional inflammatory cytokine produced by many different cell types, including adipocytes, and it is well known that circulating and adipose tissue levels of IL-6 are elevated in obese subjects and linked to the metabolic and vascular complications of obesity." (PMID 35335277, 2022). "Moreover, the development of liver cancer promoted by obesity depends on the production of tumor promoting cytokines IL-6 and TNF, which can cause liver inflammation and activation of oncogenic transcription factor STAT3." (PMID 35422001, 2022). "Indeed, we discovered that TCZ ameliorated the impact caused by Kyn-induced IL-6, indicating that the effect of Kyn on obesity and insulin resistance is mediated by IL-6." (PMID 35715443, 2022). "However, the results of one study indicate anti-inflammatory properties and the homeostatic role of IL-6 in obesity-associated inflammation and IR." (PMID 35620114, 2022). "Some other studies have revealed a regenerative property of IL-6, thus suggesting that IL-6 elevation observed in obesity may be one of the underlying mechanisms through which β-cells self-adapt and regenerate under stressful inflammatory conditions." (PMID 35628332, 2022). "The production of pro‐inflammatory adipocytokines including TNF‐α and IL‐6 is upregulated, whereas that of anti‐inflammatory adipocytokines such as adiponectin is downregulated in AT in association with obesity, with such changes contributing to inflammatory changes in MetS." (PMID 35005845, 2022). "Since obesity is associated with increase IL-6 levels, this may explain why those results differ from ours." (PMID 35173631, 2022).
Obesity (continued). "Chronic systemic inflammation associated with obesity, and particularly IL-6 among cytokines, is also involved in the induction of insulin resistance and chronic hyper-insulinemia, which, in turn, are independent risk factors for the development of endometrial cancer." (PMID 35053431, 2022). "Likewise, some microRNAs are linked to obesity-induced inflammation through pro-inflammatory pathways, such as NF-κB and the pro-inflammatory cytokines TNFα and IL-6." (PMID 36355127, 2022). "The present study was designed to clarify whether IL-6R deficient mice phenocopy the IL-6 deficient mice in diet-induced obesity and physical exercise exposure." (PMID 36387898, 2022). "IL-6 is secreted in brown adipocytes, causing brown adipocytes to fail to regulate the metabolism of glucose and to decompose fat, which ultimately leads to obesity." (PMID 35668772, 2022). "Systemic levels of IL-6 are elevated in association with obesity and B-WATi21." (PMID 35087024, 2022). "Further studies are warranted to investigate asthma treatment effectiveness in childhood-onset asthma patients with obesity, early lifestyle weight-loss intervention strategies, and molecular therapeutic targets, such as adiponectin and the IL-6 trans-signaling pathway." (PMID 36253437, 2022). "Obesity caused alteration of plasma adiponectin, IL-6 and TNF-α in TNBC patients." (PMID 35964108, 2022). "Additionally, evidence shows that activated adipocytes are one of the main sources of the IL-6 and IL-8 production in obesity-associated IR and also in GDM." (PMID 36498901, 2022). "IL-6 is a cytokine associated with obesity and insulin resistance." (PMID 35474339, 2022). "Considering IL-6, chronic elevations were reported in association with older age and obesity." (PMID 35479493, 2022). "Furthermore, IL-6 can stimulate alternative M2 macrophage activation, which is implicated in the protection from obesity-induced chronic inflammatory systemic and insulin resistance, reinforcing the importance of our findings." (PMID 35453736, 2022). "It has been reported that dolutegravir induces the release of IL-6 by adipocytes which may potentiate the systemic inflammation associated with obesity." (PMID 36558190, 2022). "IL-6 is a pro-inflammatory cytokine, which is associated with diabetes and obesity." (PMID 35422001, 2022). "HOMA-IR and interleukin 6 levels confounded the association between obesity and high TTV levels, which suggests that insulin resistance and chronic low-grade inflammation might both contribute to the observed difference." (PMID 36246898, 2022). "Animal studies have emphasized that obesity is associated with adipose tissue inflammation and oxidative stress in the liver, and certain Lactobacillus strains can reduce the transcription of proinflammatory cytokine genes, such as IL-6, TNF-α and IL-1β." (PMID 36345438, 2022). "Therefore, bodyweight reduction through a hypocaloric diet decreases visceral adipose tissue, Leptin, IL-6 and IL-1a while increasing ketone bodies, attenuating inflammatory response linked to psoriasis and obesity." (PMID 35886846, 2022). "Obesity is a risk factor of PE and has been relevant to increased inflammation due to elevated levels of interleukin-6 (IL-6), which is a vital regulator of hepcidin and thus may be associated with iron dysregulation." (PMID 35883776, 2022). "Among 600 potential adipokines, IL6 has deserved a special interest because it could be related to insulin resistance and hence associated with obesity." (PMID 35111744, 2021). "In diet-induced obesity mouse model endothelial autophagy deficiency induced IL6-dependent EndMT." (PMID 33927720, 2021). "And indeed, not only IL-6-deficient mice but also mice with hepatocyte-specific gp130-deficiency display strongly impaired tumour formation not only in a murine DNA damage-driven HCC model but also in an obesity-driven liver tumour model." (PMID 34047814, 2021).